INS (insulin)
Diseases named in the same sentence as INS in open-access papers (continued):
Sharing a sentence is not in itself a finding about the gene and the disease.
Obesity (continued). "In summary, the data of our present study revealed a synergistic, or at least a beneficial additive, effect of the combination of metformin and pioglitazone on the improvement of glucose and lipid metabolism and insulin sensitivity in HFD-induced obesity and IR mice." (PMID 36304148, 2022). "In this triple-tracer positron emission tomography study, we investigated whether brain insulin signaling, μ-opioid receptors (MORs) and cannabinoid CB1 receptors (CB1Rs) are associated with risk for developing obesity." (PMID 34728775, 2022). "Abnormal increases of the insulin level may have adverse effects on the body, such as the excessive accumulation of fat and eventually obesity." (PMID 36005612, 2022). "Moreover, the impact of short-chain fatty acids (SCFAs) and succinate (microbial metabolites) on the microbiome promotes improvement in obesity-related insulin sensitivity in animals and influences mass control and glucose and lipid homeostasis in humans." (PMID 35268466, 2022). "Recent data suggest that Ad-EVs might participate in the alteration of whole-body glucose metabolism through their deleterious actions on SkM insulin-induced glucose uptake in the context of obesity." (PMID 35806052, 2022). "Certain common features of adiposity that are observed in obesity-induced CRC patients are the increased presence of free fatty acids, lipids, and cholesterol levels; moreover, the increased concentration of insulin in the serum is also associated with increased CRC risk." (PMID 36429114, 2022). "Such a discrepancy may be attributed to: firstly, the level of insulin secretion and sensitivity greatly differs by ethnicity; secondly, obesity, which plays an important role in IR; thirdly, difference in sample size." (PMID 36589794, 2022). "Recently, it was suggested that the possibility of increased autophagy activity induced by obesity might act as a compensatory signal to reduce insulin resistance and inflammatory responses in adipose tissue." (PMID 36499655, 2022). "Aging diminishes the ability to secrete insulin, whereas obesity decreases insulin sensitivity." (PMID 36118835, 2022). "Moreover, plasma EVs from women with obesity induce impaired insulin-stimulated glucose uptake in a human adipocyte cell line." (PMID 36274855, 2022). "Moreover, circulating IGFBP-2 levels are associated with reduced insulin sensitivity in obesity patients, and the decrease in IGFBP-2 post-surgery indicates an increase in insulin sensitivity." (PMID 35159232, 2022). "Blocking the SUMOylation of PPARγ at Lys107 in mice can achieve enhanced insulin sensitivity without causing excessive obesity." (PMID 36551260, 2022). "We show for the first time that our mouse model of maternal obesity recapitulates this, with increased levels of sFlt in the obese dams and reduced uterine artery compliance that correlates positively with maternal fasting insulin levels." (PMID 34505282, 2022). "However, when fed a HFD, the huREG4IECtg mice showed marked resistance to HFD-induced obesity, including reduced whole body and fat pad tissue weights and increased insulin sensitivity and glucose tolerance." (PMID 35074011, 2022). "An obesity-related host microbiome displays an enrichment in particular gene categories involved in carbohydrate and lipid metabolism and a decrease in enzymes involved in glucose and insulin signalling pathways." (PMID 35448499, 2022). "This study suggests that reduction of placental insulin in dams with hyper-nutrient conditions such as obesity and hyperinsulinemia (i.e., PCOS) may improve metabolic health of the offspring." (PMID 35327377, 2022). "Insulin levels rise and insulin sensitivity decreases with obesity." (PMID 35743808, 2022).
Obesity (continued). "Nonetheless, the insulin secretion was still higher than that of the patients in the other three subgroups of obesity (median insulinAUC 14390 vs. 5797–12319 mU/I·min in the other three subgroups) and in the NW controls (median insulinAUC 6915 mU/I·min) at 12-month post-surgery." (PMID 36407309, 2022). "However, we have recently found that the ISR is greater in people with obesity than in people who are lean, even when both groups are matched by basal plasma glucose concentration and hepatic and muscle insulin sensitivity." (PMID 34905513, 2022). "We conclude that the use of this specific p70S6K inhibitor hampers the onset of obesity and associated disturbances, such as the progression of fatty liver and hypertriglyceridemia, even though insulin sensitivity did not improve in our treated mice." (PMID 35737463, 2022). "As outlined by the ‘accelerator hypothesis’21, increased stress on insulin demands in children with obesity may contribute to earlier β-cell failure and subsequently an earlier diagnosis of T1D22." (PMID 35484151, 2022). "Given that GDM is a more hyperglycemic, insulin resistant, and pro-inflammatory state than is obesity, we hypothesized that milk produced by women with GDM may have even higher concentrations of these factors than seen in obese women without GDM." (PMID 35277026, 2022). "Lastly, future studies on insulin index diets may assist in developing new dietary interventions for adolescents with obesity and IR, but this assumption needs to be confirmed by further clinical trials." (PMID 36364954, 2022). "Cortisol activation relies heavily on 11β-HSD1 and it has been suggested that the inhibition of this enzyme may provide a target for T2D and obesity treatments, acting to improve insulin sensitivity." (PMID 36246869, 2022). "Adipose tissue from insulin-resistant subjects presents DNA hypermethylation of different genes, such as FTO (associated with increased risk of obesity and cardiovascular diseases) and IGF2 (associated with a higher triglyceride/HDL ratio and increased metabolic risk in children) genes." (PMID 35562979, 2022). "Recent studies suggest that BCAAs are not just associated with obesity and T2D, two strong risk factors for AD, but they also are capable of impairing glycemic control and insulin sensitivity." (PMID 36359919, 2022). "Despite their obesity, mitoNEET overexpression during high caloric intake resulted in system-wide improvements in insulin sensitivity, providing a model of a metabolically healthy, obese state that minimizes lipotoxicity in tissues that are prone to storing lipids during excess caloric intake." (PMID 36077011, 2022). "In addition, recombinant hyaluronidase PH20 (PEGPH20) was found to significantly reduce adipose tissue mass and adipocyte size and improve insulin sensitivity in a mouse model of diet-induced obesity." (PMID 36233143, 2022). "Therefore, large increases in the concentrations of amino acids in plasma can mask possible impairments in insulin-stimulated blood flow in muscle that directly impair amino acid delivery and, thus, protein synthesis in muscle of humans with obesity." (PMID 35350688, 2022). "However, recent reports indicate that overexpression of PPARγ2 specifically in pancreatic β Cells impaired insulin signaling and insulin secretion, exacerbated obesity-induced glucose intolerance and reduced β cell mass." (PMID 36568082, 2022). "•Diet-induced obesity alters the function and increases the levels of hindbrain insulin." (PMID 36244663, 2022). "Given the critical role of Foxa2 in regulation of insulin signaling 6, 28-32, this observation motivated us to dissect the role and mechanism of action of this transcription factor in a high-fat diet induced obesity mouse model." (PMID 35154496, 2022). "In addition, elevated plasma glucose and insulin levels, obesity, and physical inactivity are also related to colorectal cancer." (PMID 36438843, 2022).
Obesity (continued). "Hence, the present study was conducted to assess the effects of daily intake of 43 g (≈1.5 oz) of almonds for 12 weeks on insulin sensitivity, insulin resistance, and serum lipid markers among Asian Indian adults with overweight and obesity." (PMID 36704786, 2022). "Indeed, increased adipocyte size has been shown to positively correlate with impaired systemic insulin sensitivity and impaired glucose tolerance in humans, independently of the degree of obesity." (PMID 36158197, 2022). "Assuming average basal insulin secretion and clearance rates in people with obesity, a 10% decrease in plasma insulin clearance would cause a ~120 pmol/L (or ~20 mU/L) increase (approximately doubling of basal values) in plasma insulin concentration in just 10 min." (PMID 35054781, 2022). "In obesity, there is impaired inhibition of lipolysis by insulin, resulting in increased levels of fatty acids and glycerol, and adipose tissue secretes cytokines and other pro-inflammatory molecules that antagonize the action of insulin and contribute to inflammation." (PMID 36248900, 2022). "Importantly, WD feeding of SERCA2a-Thr484Ala mice led to a similar degree of obesity and systemic insulin resistance as that of WT mice." (PMID 37583938, 2022). "Moreover, when the body is suffering from metabolic abnormalities, such as obesity, SOCS3 is involved in the inhibition of inflammatory cytokines and crucial hormones linked to energy metabolism, such as insulin signaling and leptin." (PMID 36145200, 2022). "Moreover, adiponectin reduction induced by obesity also decreases insulin sensitivity, although it increases the circulating insulin level, which inhibits AMPK activity in muscles and thereby slows down fiber-type expression." (PMID 35267959, 2022). "Subgroup analysis of our findings showed that trial duration, intervention dose, and BMI status significantly affect the insulin level, as well as, it was shown that trial duration, intervention dose, obesity, and health status have a significant effect on the HOMA-IR levels." (PMID 36704801, 2022). "In addition, the HFO diet can lead to decreased lipid accumulation, obesity, and insulin sensibility compared to HL." (PMID 35898328, 2022). "While B1R deficiency did not prevent obesity, those mice were able to overcome the loss of the insulin sensitivity with a substantial increase in the insulin secretion, which can possibly explain why they had a lower glycemic response during GTT." (PMID 35617279, 2022). "Leptin might play a role in β-cell compensatory insulin hypersecretion, particularly in the state of leptin resistance that occurs in obesity." (PMID 35628332, 2022). "As obesity promotes a low grade of chronic inflammation, and due to the observed effects of PomE in the improved insulin sensitivity and the increased on EE and thermal temperature after cold exposition, we next evaluated the effects of PomE on markers of inflammation after HFD exposition." (PMID 36142372, 2022). "Obesity, especially visceral obesity, is negatively correlated with insulin sensitivity." (PMID 35562979, 2022). "MDSCs also suppress inflammation and promote insulin sensitivity in obesity." (PMID 36052717, 2022). "For example, a plethora of evidence supports that WD rich in salts, fried food and non-meat related fats impair glucose and insulin metabolism, causing chronic diseases including T2D, obesity and CVDs." (PMID 35807769, 2022). "Increased levels of insulin, triglyceride, total cholesterol, LDL cholesterol, CRP-U, AST, ALT, GGT, free T4, IGF-1, and uric acid and low levels of HDL cholesterol are found to be associated with a higher chance of obesity." (PMID 35703718, 2022). "In summary, obesity not only facilitates the infiltration of inflammatory immune cells into adipose tissue but also disables the protective mechanisms required to maintain insulin sensitivity and glucose homeostasis." (PMID 34837070, 2022).
Obesity (continued). "In diabetic mice, administration of Bacteroides acidifaciens and B. uniformis prevented obesity and improved insulin sensitivity suggesting that Bacteroides may have beneficial effects." (PMID 35886861, 2022). "The use of a small‐molecule inhibitor of PKD2 as well as PKD1 and PKD3 (CRT0066101), also allowed a localized inhibition of this pathway in the small intestine, thereby decreasing intestinal lipid absorption to ameliorate obesity and restore insulin sensitivity." (PMID 35437952, 2022). "Examination of the systematic evidence presented for the effect of long-term intervention with low GI and GL on fasting insulin level and proinflammatory markers showed that it could effectively prevent obesity-related disease." (PMID 35433797, 2022). "In our study cohort, pre-pubertal children with obesity and with low z-scores of circulating leptin levels are characterized by an altered metabolic profile including higher triglyceride, insulin and c-peptide concentrations compared to children with normal z-scores of circulating leptin levels." (PMID 35677722, 2022). "Insulin was a strong mediator in the relationship between obesity and hyperglycemia." (PMID 35757631, 2022). "Taken together, our data reveal that the major mechanism for PC1/3 deficiency-associated obesity is not a defect in central processing and we suggest that the pancreatic β-cell-derived insulin is a major player in this pathology." (PMID 35963866, 2022). "Moreover, there seems to be a sex-dependent role of insulin on microglial immune and phagocytic function during health and obesity." (PMID 35328354, 2022). "In addition, improvements in insulin sensitivity and glucose tolerance were observed in miR-143KO mice, which further support the anti-obesity of miR-143KO." (PMID 36361843, 2022). "Obesity, a low-grade, chronic inflammatory condition, increases ATMs and abnormal cytokine secretion and impairs macrophage metabolism by increasing the M1 phenotype, which acts as an obstacle to insulin signaling." (PMID 36499655, 2022). "Additionally, the specific interaction of dietary macronutrients and the endocrine system, in particular insulin response and signaling, has a critical role in the etiology of obesity." (PMID 35945490, 2022). "From the energy supply point of view, insulin resistance represents the most plausible link between obesity and higher TG, which may lead to increased lipolysis, adiposopathy, and release of free fatty acid (FFA) into the circulation." (PMID 35805464, 2022). "Thus, in the presence of a pro-inflammatory molecule that resembles an obesity condition, the action of insulin sensitizers can re-establish the expression of molecules to improve insulin signaling in endometrial cells." (PMID 35409282, 2022). "Thus, GCBE administration enhanced insulin sensitivity in obese rats, which was confirmed by alleviating obesity-related hyperinsulinemia and HOMA-IR decline." (PMID 35629362, 2022). "Further, miR-26a regulates both glucose metabolism and insulin signaling, as an expression of miR-26a in the liver was decreased in obesity, which might suggest its potential role as a biomarker for obesity-related metabolic complications." (PMID 36517853, 2022). "However, BRS-3 has been identified as an important regulator of satiety, metabolic rate and obesity in the brain, glucose uptake in muscles, insulin secretion in β-cells, and glucose uptake and lipogenesis in adipose tissue." (PMID 35347148, 2022). "Moreover, these analysis can be influenced by different metabolic and hormonal variables, such as blood glucose levels, insulin levels, testosterone levels, ovarian hormone levels, obesity, and caffeine intake." (PMID 36568110, 2022). "Sufficient human and animal studies have proved that SCFAs and BAs are associated with obesity and metabolic disorders, and they are involved in the processes of nutrient intake, insulin secretion, and immunity to affect the characteristics of obesity in hosts." (PMID 36092861, 2022).
Obesity (continued). "Here, we aimed to explore whether genistein regulates glucose and hepatic lipid by activating the insulin signaling pathway in diet-induced obesity mice." (PMID 36570152, 2022). "Mothers with pregestational obesity received the highest amount of insulin." (PMID 35663318, 2022). "Bacteroides acidifaciens and Bacteroides uniformis induce Glucagon-like peptide-1 (GLP-1) activation by using the G-protein-coupled bile acid receptor (TGR5) through bile acids, taurine, and cholate that counters obesity and increases insulin sensitivity in mice." (PMID 36229889, 2022). "The authors speculate that a low-II diet may reduce nutrient-induced hyperinsulinemia and lead to a greater improvement in IR and insulin sensitivity in adolescents with obesity." (PMID 36364954, 2022). "As FGF21 treatment in animal obesity models resulted in reduction of adiposity, improved insulin sensitivity, a decrease of cholesterol and triglyceride levels, FGF21 was suggested to have potential as a novel therapy for obesity and related diseases like T2D and PCOS." (PMID 36289764, 2022). "Adiponectin can prevent the impairment of insulin signaling, so CXCL8 may plays a crucial and causal role in obesity-linked IR and GDM." (PMID 35211112, 2022). "During obesity, the inflammation in pancreatic islets makes β cells fail to secrete insulin." (PMID 35574038, 2022). "As a result of the comprehensive management presented in the one-day outpatient service, the blood glucose levels of these participants decreased compared with their initial levels; however, the overweight and obesity group still reported the highest levels of insulin utilization." (PMID 36960096, 2022). "This high rate of obesity may be due to the agents used in the treatment of T2DM, including insulin, sulfonylureas, and thiazolidinediones, which promote weight gain Obesity increases the health risks of T2DM and complicates its management." (PMID 35655685, 2022). "Sucrose-induced obesity has been related to memory decline subsequent to hippocampal IR, which results from elevated glucose and triglyceride levels that penetrate the blood–brain barrier and interfere with insulin signaling." (PMID 35883886, 2022). "In addition to unreasonable diet and lack of exercise, PCOS patients are more likely to have abnormal glucose and lipid metabolism due to poor insulin sensitivity, so the probability of obesity is significantly higher than that of normal women." (PMID 36248406, 2022). "Our data suggest that the effect of RAPA on obesity and improved systemic insulin sensitivity may be mediated partly through downregulation of MEST‐facilitated fat mass expansion and the related tissue hypoxia and adipose tissue inflammation." (PMID 35986566, 2022). "With overweight and obesity the adipose tissue in general change its phenotype from been anti-inflammatory and insulin-sensitive to be pro-inflammatory, pro-thrombotic and insulin resistant, in addition to undergo hypertrophy and increase the release of free fatty acids." (PMID 36644557, 2022). "As supporting reports, preventive potential in obesity and metabolic syndrome of polymerized catechins in green tea anticipated by its anti-obesity activity and improvement of insulin resistance, vascular function, and cardiac hypertrophy was signified in the green tea products." (PMID 36014557, 2022). "Likewise, evidence from in vitro models suggests that adipocytes stimulated in conditions simulating obesity and IR, communicate with adjacent adipocytes promoting hypertrophy and affecting insulin signaling through EVs." (PMID 35681526, 2022). "However, GDM patients with obesity required a higher amount of rapid acting insulin as compared to normal weight patients." (PMID 35663318, 2022). "Collectively, these findings suggest that PAR2 does not attenuate age-associated obesity or insulin action." (PMID 36235747, 2022).